TLR7 (toll like receptor 7)
Diseases named in the same sentence as TLR7 in open-access papers (continued):
Sharing a sentence is not in itself a finding about the gene and the disease.
lupus (continued). "In lupus patients, immature B cells are regulated by sensors of viral RNA such as TLR-7 and can differentiate into extra-follicular double-negative memory B cells (CXCR5-CD11c+)." (PMID 39917309, 2025). "Therefore, TLR7 and TLR9 signals and IL-21 and IFN-γ play critical roles in ABC differentiation in lupus mice." (PMID 39960645, 2025). "TLR7 activation by endosomal ssRNA, notably ERV RNA in autoreactive B cells, critically contributes to the pathogenesis of autoimmune diseases such as systemic lupus erythematosus (SLE), with compelling evidence from both murine models and human patients." (PMID 41190279, 2025). "For example, in the lupus microenvironment, factors such as IFN-α and TLR-7 agonists could shift the MDSC differentiation towards M-MDSCs along with an increased level of IRF-8 while decreasing G-MDSCs." (PMID 40725182, 2025). "In addition, TLR7 and NLRP3 expression was significantly increased in the lupus groups, although it was significantly less pronounced in the CLC group." (PMID 40507090, 2025). "Chronic IFN-α production is a risk factor for autoimmune diseases, such as systemic lupus erythematosus; therefore, it is reasonable that neither PBMCs produce IFN-α nor LF induces its production unless TLR7 signals an emergency." (PMID 39769133, 2024). "BCAT1 may therefore constitute an intriguing metabolic vulnerability, including in MCD DLBCL and in certain autoimmunity states, including systemic lupus erythematosus, where BCR/TLR7 drives pathology." (PMID 38854072, 2024). "To explore whether S100A8/9 contributes to the promotion effect of lupus MDSCs through activation of the TLR7 pathway, we first investigated whether S100A8/9 can regulate the TLR7 pathway activation." (PMID 38429401, 2024). "In fact, numerous animal studies in which TLR7, TLR9, or the related signaling factor Myd88 was deleted demonstrated remission of related auto-antibody production in murine lupus, whereas transgenic over-expression provoked B cell stimulation and formation of germinal centers (GCs)." (PMID 39456692, 2024). "For example, both MDA5 and cGAS were upregulated in in vitro maturated splenic B cells from a TLR7 agonist-induced lupus model, while the MDA5 pathway was also activated without additional stimulation with CD40L." (PMID 38791389, 2024). "Additionally, to confirm the role of Bank1, through TLR7-dependent pathway, in the control of the ABC population, we evaluated the percentage of ABCs in a third lupus model, the B6.Sle1." (PMID 39163122, 2024). "Disease exacerbation was abrogated when TLR7 was also deleted from TLR9 null mice, indicating that TLR9 could limit lupus pathogenesis by diminishing the deleterious effects of TLR7." (PMID 39000140, 2024). "More recent work revealed that in lupus mice that lacked Tlr9 systemically, conditional ablation of Tlr7 in B cells ameliorated disease." (PMID 39310226, 2024). "Several experimental models of lupus exist, with a more recently described model being topical treatment with imidazoquinoline derivatives such as imiquimod (IMQ), which are recognized by TLR7." (PMID 38346802, 2024). "Furthermore, the proportion of IgG2c+ ABCs was also significantly decreased in TLR7.tg6.Bank1–/– and IMQ-treated Bank1–/– mice compared with Bank1-sufficient lupus-prone mice." (PMID 39163122, 2024). "We therefore examined whether ZEB2 regulated ABC-mediated autoimmunity in lupus induced by IMQ, a TLR7 agonist." (PMID 38271512, 2024). "Pioneering related work has revealed that global knockout of GSDMD exacerbated autoimmunity and renal inflammation in a TLR7 agonist-induced lupus model without elucidating the mechanism." (PMID 38831451, 2024). "However, although they exhibit similar tissue expression and are involved in similar signaling pathways, TLR7 and TLR9 have opposing inflammatory and regulatory roles in lupus-prone MRL/lpr mice." (PMID 36769633, 2023).
lupus (continued). "Also, in the plasma of patients with systemic lupus erythematosus (SLE) activation of plasma cell-like DC and production of proinflammatory cytokines and IFN-α can be induced by TLR7 endogenous ligands within exosomal delivered miRNA." (PMID 37605155, 2023). "Type 1 IFN produced by pDCs has beneficial roles in host immunity to viral infections, but it is also implicated in the pathogenesis of certain types of autoimmune diseases, including systemic lupus erythematosus (SLE), especially through an aberrant TLR7 activation." (PMID 38077311, 2023). "Recent work highlighted a population of CD27 and IgD double-negative B-cells that are hyper-responsive to TLR7 signaling and expanded in lupus patients." (PMID 36845162, 2023). "Furthermore, Ly6Chi inflammatory MOs and T cells had significantly increased BAFF expression per cell in both spontaneous lupus models, while CD8- DCs up-regulated BAFF expression only in the Tlr7 Tg mice." (PMID 36923413, 2023). "In this study, we examined the effect of a treatment with a TLR7/8 agonist in the B6.Sle1.Sle2.Sle3 triple congenic (TC) mouse, a spontaneous mouse model of lupus without gut leakage." (PMID 37483626, 2023). "TLR7/8 activation impaired gut integrity in lupus-prone TC mice but not in congenic controls based on the FITC-dextran assay, and it lowered the expression of Claudin-1 between gut epithelial cells and PECAM1 between blood/lymphatic endothelial cells." (PMID 37483626, 2023). "TLR7/9 antagonists, compound 29 and IRS-954 (immunoregulatory DNA sequence-954), showed therapeutic efficacy in a preclinical murine model of psoriasis and lupus, respectively." (PMID 35619184, 2022). "IT1t was also shown to inhibit TLR7-mediated type I interferon (IFN) signaling in human plasmacytoid dendritic cells (PDCs) from the blood and tonsils, thereby reducing inflammation in patients with systemic lupus erythematosus (SLE)." (PMID 35893797, 2022). "Thus, the roles and the relationship between TLR7 and TLR9 in lupus immune signaling have gradually received increasing attention and have been investigated." (PMID 36555668, 2022). "Both TLR and IL-1R family members drive MyD88-dependent inflammation, and TLR7 is a MyD88-dependent endosomal TLR that has been shown to be of critical importance in several autoimmune diseases, most notably Systemic Lupus Erythematosus (SLE) or lupus." (PMID 36591307, 2022). "Although circumstantial evidence supports enhanced Toll-like receptor 7 (TLR7) signalling as a mechanism of human systemic autoimmune disease, evidence of lupus-causing TLR7 gene variants is lacking." (PMID 35477763, 2022). "To elucidate the effect of EPA on the progression of SLE, we first induced lupus in wild-type FVB/N mice using imiquimod (IMQ), a TLR7 agonist, and prophylactically fed the mice a diet supplemented with 5% EPA or 5% palmitate as a control to match caloric intake." (PMID 34211460, 2021). "TLR7 activation was probably required for the increases in these monocytes in mice with lupus, but not in healthy mice, and the anti-TLR7 mAb inhibited TLR7-dependent increase of monocytes." (PMID 34868046, 2021). "TLR7, an important mediator of the innate immune response, drives the expression of type-1 interferon (IFN), which leads to expression of type-1 IFN induced genes and aggravates lupus pathology." (PMID 33444326, 2021). "Murine experimental lupus induced by transgenic Tlr7 overexpression is ameliorated in the absence of B cell autophagy." (PMID 34163480, 2021). "In summary, we have demonstrated that there was a critical threshold level of IRF5 in B cells that was required for disease development in the FcγRIIB−/−Yaa mouse lupus model and that IRF5 nuclear translocation was substantially reduced in B cells from IRF5-heterozygous mice after TLR7 activation." (PMID 34197340, 2021).
lupus (continued). "Topical administration three times per week in alternate days to wild-type BALB/c mice of IMQ, a TLR7 agonist, successfully induced a lupus-like pathology in our animals not genetically prone to excessive TLR7 signaling." (PMID 35052589, 2021). "BXSB/Yaa mice in which the TLR7 gene is duplicated develop an autoimmune disease similar to ABIN1[D485N] mice and the spontaneous development of lupus in several other lupus-prone mouse lines is attenuated by crossing to TLR7 KO mice." (PMID 31694920, 2019). "To further determine whether exacerbated lupus and metabolic abnormalities observed in HFD- vs. SD-fed TLR8ko mice could be attributed to augmented TLR7 signaling, we next evaluated TLR7 expression levels." (PMID 31552019, 2019). "The B6 mice had low positive ANA titers, but no lupus-like renal disease, and thus would not be an optimal WT strain for use as a TLR7-induced lupus model." (PMID 31998321, 2019). "We used a topical TLR7 agonist, previously reported to induce lupus-like disease in WT mice within weeks, to validate this data in C57BL/6j mice, and to test TLR7 agonism as an accelerant in lupus-prone NZM2410 mice." (PMID 31998321, 2019). "Thus, it is quite rational to consider this epicutaneous TLR7-inducible phenotype, which is pDC-dependent and partially IFN-dependent, as a viable lupus animal model." (PMID 31998321, 2019). "The data presented in this paper demonstrated that CD180, low-expressed in macrophages and DCs from SLE patients and lupus-prone MRL/lpr mice, could negatively regulate TLR7- and TLR9-mediated activation of macrophages and DCs in vivo and in vitro." (PMID 30498494, 2018). "TGF-β3 ameliorates IL-10-sufficient lupus-prone MRL/Faslpr/lpr (MRL/lpr) mice, but the requirement of both TGF-β3 and IL-10 in the regulation of other lupus models induced with a TLR7 agonist implies the importance of considering ICS when designing future therapeutic strategies." (PMID 30071700, 2018). "We, therefore, used ligands against TLR7 (R848) and TLR9 (CpG-A and -B) and also directly stimulated cells with recombinant IFN-α to test if the ISGs’ expression was modulated by BKs in normal and lupus-prone mouse DCs." (PMID 29456540, 2018). "In addition, in kidney biopsies from patients with lupus nephritis (LN), there was evidence of TLR3, TLR7, and TLR9 overexpression with a positive correlation between TLR9 expression and high activity, measured by renal-systemic lupus erythematosus (R-SLEDAI)." (PMID 30034390, 2018). "For instance, TBK1 is not required for IFN-I production in the TLR7-dependent pristane-induced lupus model." (PMID 29559975, 2018). "More recently, TLR7 signaling was confirmed to be necessary for optimal B cell survival and GC formation both in nonautoimmune and in lupus-prone mice." (PMID 27635115, 2016). "However, activating TLR7 by CL095 together with co-activation of BCR can promote IL6 production by B cells, especially in B cells from lupus-prone mice." (PMID 26068236, 2015). "In addition to Type I IFNs, splenic DCs produce various cytokines in response to TLR7/TLR9 stimulation by anti-chromatin immune complexes (IC), which are a driving factor of lupus pathology." (PMID 25093822, 2014). "TLR9 recognizes dsDNA with a CpG motif and, unlike TLR7, it does not accelerate disease in murine lupus." (PMID 25147296, 2014). "However, the discovery of TLRs in humans opened a new field in the studies of lupus, and our study of TLR3, TLR7, and TLR9 confirms their potential influence on the disease." (PMID 24692849, 2014). "Therefore, we believe, based on our data that treatment should not only target TLR7/8 and TLR9, but also should target the effect of TLR4 signaling on lupus pathogenesis, and gender differences in other autoimmune diseases." (PMID 25485543, 2014). "TLR7 and TLR9 have been extensively studied using lupus-prone mouse models." (PMID 25538618, 2014).
lupus (continued). "As dysregulated TLR signaling, particularly through TLR7 and TLR9, may contribute to lupus pathogenesis it is possible that the effects of IRF5 in lupus are mediated through alterations in the strength or nature of TLR signaling events." (PMID 25076492, 2014). "Oligonucleotides that inhibit the response to TLR7 and TLR9 ameliorate disease in lupus-prone mice." (PMID 23772226, 2013). "In conclusion, prednisolone and TLR antagonist (hydroxychloroquine) may down-regulate expression levels of TLR7 and TLR9 in lupus patients, thereby decreasing the innate immune response to HPV infection." (PMID 22513098, 2012). "In summary, we have provided evidence that TLR7 activation for the enhanced LMP1 expression and this mechanism may be present in lupus in vivo." (PMID 22952664, 2012). "TLR7 and TLR9 appear to have different roles in the development of murine lupus." (PMID 22110541, 2012). "Upregulated expression of TLR-7 and TLR-9 mRNA, together with IFN-γ mRNA in PBMC, may also contribute to the pathogenesis of human lupus." (PMID 22312407, 2012). "In conclusion, prednisolone and TLR antagonist (hydroxychloroquine) may down-regulate protein levels of TLR7 and TLR9 in lupus patients, thereby decreasing the innate immune response against HPV infection." (PMID 22513098, 2012). "In contrast, lupus-prone MRL/Mplpr/lpr mice lacking TLR7 showed impaired production of antibodies to RNA-containing antigens, such as anti-Smith (anti-Sm) antibodies, and developed less severe disease." (PMID 21396113, 2011). "In the current study, we characterized the role of the IFNAR2 chain of the type I IFN (IFN-I) receptor in the targeting of nucleic acid-associated autoantigens and in B-cell expression of the nucleic acid-sensing Toll-like receptors (TLRs), TLR7 and TLR9, in the pristane model of lupus." (PMID 19624844, 2009). "However, to our knowledge, the interaction of cinnamon with TLR7-dependent pathophysiological pathways has not yet been elucidated, and cinnamon has never been tested as a disease modifier in lupus." (PMID 40507090, 2025). "In this study, we investigated the role of spinal TLR7 in the pathogenesis of chronic pain using female MRL lupus prone (MRL/lpr) mice, a SLE mouse model." (PMID 41511304, 2025). "TLRs play a crucial role in B cell activation; BCR-driven immune complex uptake stimulates TLR-7 and TLR-9, which further activates the type I interferon response in B cells and enhances the production of autoantibodies, contributing to the pathogenicity of lupus." (PMID 39917309, 2025). "As circulating nucleic acid-containing complexes can stimulate plasmacytoid dendritic cells (pDCs) in systemic lupus erythematosus, some intracellular Toll-like receptors (like TLR3, TLR7, TLR8, TLR9) and their signaling pathways could be potential therapeutic targets." (PMID 41573545, 2025). "Furthermore, activation of spinal TLR7 by incubating normal spinal cords (n = 4) with DSR 6434 (2 μM) for 2.5 h significantly increased Cav2.2 expression in the dorsal horn, reproducing the pathological change observed in lupus mice." (PMID 41511304, 2025). "Conversely, as in the case of viral infections, we do not expect the SLC15A4-TASL complex to be involved in TLR7/9- and IRF5-independent autoinflammatory and autoimmune models, such as the lupus-like manifestations observed upon TREX1-deficiency which relies on the STING pathway." (PMID 39856058, 2025). "A non-significant trend toward higher TLR7 expression was observed in the lupus group." (PMID 39061948, 2024). "Our results indicate that MDSCs may aggravate the pathogenesis of TLR7-mediated lupus by promoting the activation of macrophages and DCs through the S100A8/9-IFN-γ axis, suggesting that MDSC-derived S100A8/9 plays a crucial role in lupus pathogenesis." (PMID 38429401, 2024).
lupus (continued). "In mice strains not prone to lupus, overexpression of TLR7 (introduction of over four copies of the TLR7 gene) was sufficient to induce a spontaneous lupus-like phenotype (glomerulonephritis, ANAs, increased serum levels of inflammatory cytokines, and increased lethality)." (PMID 38255243, 2024). "Four small molecules, dual inhibitors of TLR7 and TLR8 (Afimetoran/BMS-986256, Enpatoran/M5049, MHV370, and E6742), have successfully passed the stage of preclinical validation in various murine models of lupus and recently entered the early phases of clinical development in humans." (PMID 38255243, 2024). "In addition, the non-redundant role of TLR7 has been well established in lupus mouse models, and enhanced expression of TLR7 is sufficient to induce full blown autoimmunity and SLE-like disease in mice." (PMID 39444662, 2024). "However, the effect of MDSCs on TLR7-mediated autoimmune responses and lupus pathogensis has not been determined." (PMID 38429401, 2024). "By genetic manipulation of mice to prevent B cells from forming GCs (CD23CreBcl6flox mice), it has been found across three Tlr7-dependent lupus mouse models – kika, 564 Igi and imiquimod-induced lupus - that the absence of GC does not alleviate the autoimmune phenotype." (PMID 38866437, 2024). "Treatment of cell cultures with the plasma of lupus mice induced a trend toward increased TLR7 expression compared to that with the plasma of sham mice and non-significantly lower expression of TLR7 after treatment with the plasma of the cinnamon-treated groups." (PMID 39061948, 2024). "Hence, we conclude that TLR7 promotes lupus by acting in B cells — not pDC or DC — particularly when the regulatory effect of TLR9 is absent." (PMID 37606042, 2023). "Moreover, a topical treatment with Resiquimod (R848), a TLR7/8 agonist, induces lupus-like manifestations in non-autoimmune mice." (PMID 37483626, 2023). "Moreover, BMS-986256 (Afimetoran) is another small molecule that blocks TLR7 and TLR8, can be delivered orally and was able to prevent lupus symptoms in animals treated before the onset of disease as well as reverse organ damage when given after symptoms had already started." (PMID 36389822, 2022). "reuteri increased over time in the feces of mice from both TLR7-dependent mice lupus models as their disease progress and in the SLE patients Moreover, L. reuteri worsens autoimmune manifestations by engaging type I interferon pathways in TLR7-dependent lupus mice." (PMID 35677055, 2022). "For example, TLR2 is associated with systemic lupus erythematosus (SLE), sepsis, psoriasis; TLR3 with sepsis; TLR4 with SLE, sepsis, and psoriasis; TLR5 with psoriasis; TLR7 with SLE, stroke, and psoriasis; and TLR9 is involved in SLE, sepsis and psoriasis." (PMID 34203170, 2021). "Consistent with the B6.Nba2 and WAS models, T1IFN signaling was also not required for TLR7-driven nephritis in NZM2328 lupus-prone mice, although we observed a moderate reduction in TLR7-mediated autoimmune B cell responses, immune complex deposition, and nephritis in B6.Sle1b mice." (PMID 34638804, 2021). "Similar to TLR7, both TLR8 and TASL are involved in the etiology of systemic lupus erythematosus (SLE), a female-biased autoimmune disease." (PMID 34858409, 2021). "Because deleting TLR7 is not sufficient to rescue MRL/lpr or Tnip1-/- mice from nephritis, other TLRs such as TLR9 might also drive the increases in lupus-associated patrolling monocytes in these mice." (PMID 34868046, 2021). "A TLR7 agonist, Imiquimod (IMQ)-induced SLE mouse model was used to explore the pathogenesis of immune complex-mediated lupus nephritis in several previous reports." (PMID 32655553, 2020). "Expression levels of TLR2, TLR7, TLR9, IFN-alpha, and LY6E (Sca-1) mRNAs in SLE patients are significantly higher than healthy controls, indicating contribution of TLR-MyD88 signaling pathways in the pathogenesis of human lupus." (PMID 31354738, 2019).